DSG2 (desmoglein 2)
Diseases named in the same sentence as DSG2 in open-access papers (continued):
Sharing a sentence is not in itself a finding about the gene and the disease.
infection (31 papers, 2013 to 2026). The state of being infected such as from the introduction of a foreign agent such as serum, vaccine, antigenic substance or organism. "This study provides comprehensive evidence that HAdV-7 utilizes CD46 and DSG2 as synergistic co-receptors to mediate efficient infection, viral replication, and inflammatory pathology." (PMID 41989164, 2026). "This study provides comprehensive evidence that HAdV-7 utilizes CD46 and DSG2 as functional co-receptors that act synergistically to mediate efficient infection." (PMID 41989164, 2026). "Other receptors, such as CD80/CD86, CD46, desmoglein 2 (DSG2) and sialic acid, are involved in infection by B or D subgroup adenoviruses." (PMID 38528632, 2024). "This restriction of HadV-B3 is unclear as DSG-2 is readily expressed on the surface, and 293A cells are generally permissive for HadV species B infection." (PMID 38793540, 2024). "HAdV-3, -7, -11, and -14 use the epithelial junction protein desmoglein 2 (DSG2) as a primary receptor for infection (30, –, 32)." (PMID 38018973, 2024). "In summary, higher binding affinities of fibers with DSG2 lead to higher infection efficiency of HAdV-7 and HAdV-55 compared to HAdV-3." (PMID 38018973, 2024). "The first assay measured the ability of JO4 to block the infection of 293 cells by a GFP-expressing Ad5/3 adenovirus vector that has the same tropism to DSG2 as JO4." (PMID 35562182, 2022). "Using a CRISPR-Cas9 screen, we identified desmoglein-2 as a receptor for UPEC during ascending infection." (PMID 33513212, 2021). "The third major protein receptor for human adenoviruses is Desmoglein 2 (DSG2), shown to enable infection by HAdV-B3, B7, B11, and B1443,44." (PMID 30765704, 2019). "Bronchial epithelial cells were immunostained for HAdV hexon antigens and DSG2, the recently described novel adenoviral apical receptor, at day 4 post infection." (PMID 26168049, 2015). "Virion-like particle dodecahedra consisting of penton base and fiber are generated in infected cells during the infection of Ad serotypes 3, 7, 11 and 14 that utilize DSG-2 as a cellular receptor." (PMID 25723153, 2015). "Adenovirus type 3 uses PtDds to promote its own infection, opening the tight junctions ahead of infection to maximize access to desmoglein-2." (PMID 28548066, 2014). "Human adenovirus serotypes Ad3, Ad7, Ad11, and Ad14 use the epithelial junction protein desmoglein 2 (DSG2) as a receptor for infection." (PMID 24204268, 2013). "Previous studies have identified CD46 and desmoglein-2 (DSG2) as potential receptors for certain group B adenoviruses; however, the receptor usage of HAdV-7 infection remains unclear." (PMID 41989164, 2026). "Human desmoglein-2 also plays a major role in infection with HAdV type 55." (PMID 38018973, 2024). "However, using receiver operating characteristic curves, we identified four to 48 candidate biomarkers of infection depending on the pathogen, including seven overlapping biomarkers (DSG2, PCBP1, MGAM, APOA4, DPEP1, GOT1, and IGFALS)." (PMID 38193073, 2023). "Notably, infection from the apical side is inefficient because DSG2 is trapped in lateral epithelial junctions." (PMID 36360292, 2022). "Three days after infection, DSG2 protein levels were assessed by WB, confirming the expected reduction in DSG2 protein level, which was of similar extent in cells inoculated with either MOI 50 or 100 (85.1 ± 5.6 % reduction compared with controls, n = 3 independent experiments; p ≤ 0.01)." (PMID 33925921, 2021). "On the other hand, initial infection of the differentiated pseudostratified layer may be facilitated by DSG2 but not limited to DSG2 positive cells suggesting the relevance of other cellular receptors for HAdV-B14p1." (PMID 26168049, 2015). "HAdVs of subgroup B utilize either CD46, or Desmoglein 2 (DSG-2) to initiate infection." (PMID 25723153, 2015). "We have recently reported that a group of human Ads uses DSG2 as a receptor for infection." (PMID 24204268, 2013).
infection (continued). "Interestingly, DSG2-negative cell line MIA PaCa-2 even showed resistance to JO4 vector infection, possibly due to the negative effect of JO4 mutation on the usage of another Ad3 receptor: CD46." (PMID 36016457, 2022). "We noted that staining of DSG2, CD46, and CAR dropped to about 50%, yet there was an increased infection of HAdV-B3, -B11, and -C5, ranging between ca 50% and up to 400%." (PMID 40980888, 2025). "The aim of this work is to determine which of the two receptors, DSG2 and CD46, is involved in the attachment of the virus to the host, and what role they play in the early stages of infection." (PMID 37921471, 2023). "The infection cycle initiates with the interaction between a cell surface receptor, such as coxsackievirus-Ad receptor (CAR), CD46, desmoglein 2 (DSG2), or sialic acid, and the distal domain of the virus capsid fiber." (PMID 35745859, 2022). "Although DSG-2 expression is lower than CD46 in all lines, the Ad3 knob can utilize both DSG2 and CD46 for infection, leading to similar transduction as HDAd5/35 capsid vectors." (PMID 35681750, 2022). "In the infection process, the knob interacts with cell surface receptors such as the coxsackievirus and adenovirus receptor (CAR), CD46, CD80/86, and desmoglein 2 (DSG2)." (PMID 33919679, 2021). "During the infection process, Ads first contact the cell surface receptors such as coxsackievirus- and adenovirus receptor (CAR), CD46, CD80/86, desmoglein 2 (DSG2) and heparan sulfate proteoplycans (HSPG)." (PMID 32370135, 2020). "The influence of the fiber shaft length on infection of DSG2-targeting Ad5/3 vectors has not been studied so far." (PMID 36360292, 2022). "Whereas binding of Ad3 fiber knobs to DSG2 can open tight junctions and expose CD46 for interaction with Ad3,38 these data suggest that DSG2 plays a more predominant role than CD46 in ONCOS‐102 viral attachment and infection of EOC cells." (PMID 31944306, 2020). "DSG-2 shedding upon virus binding occurs on cells that are already infected, so shedding does not inhibit infection, but does open up intercellular spaces." (PMID 32957644, 2020). "In our study using cardiotropic CVB3 infection, we found that besides virus-activated caspase-3, CVB3 protease 3C, but not 2A, could also cleave DSG-2 and generate a ∼55-kDa intracellular fragment during infection." (PMID 32457708, 2020). "Therefore it can be concluded that in contrast to CAR, CD46 plays a role for HAdV17GFP infection, whereas DSG2 has no role as receptor for HAdV17GFP infection." (PMID 30194327, 2018). "However, although apparently able to utilize DSG-2 as receptor, the Ad5/3 chimeras are not completely dependent on DSG-2 even in vitro, as demonstrated by less efficient blocking of infection by recombinant DSG-2 in competitive assays." (PMID 23585829, 2013). "Furthermore, competition assays with pseudotyped viruses suggested that the interaction of the HAdV-11 fiber with DSG2 was not required for infection but that DSG2 could serve as a receptor in the absence of CD46." (PMID 37921471, 2023). "Thus, HAdV55 may recognize tree shrew desmoglein-2 but not CD46 for infection; however, a series of experiments needs to be performed to draw a conclusion." (PMID 33622191, 2021). "In this study, we demonstrate that HAdV-D types preferentially use CD46 for entry and infection, rather than CAR, DSG2, or sialic acid-containing glycans." (PMID 40980888, 2025). "To investigate the receptor usage, we determined the transduction capacity of HAdV-20-42-42-Luc in various cell lines, expressing or lacking CAR, sialic acid-containing glycans, DSG2, or CD46 isoforms, by measuring the luciferase levels after infection." (PMID 34469243, 2021). "Similarly, we observed a modest reduction of both DSG2 and CAR on A549-ΔCD46, which was accompanied by a slight reduction of HAdV-D37 infection (but not of HAdV-B3 or HAdV-C5) in these cells." (PMID 40980888, 2025).
heart disease (13 papers, 2013 to 2026). "Arrhythmogenic cardiomyopathy (AC) is a heart disease often caused by mutations in genes coding for desmosomal proteins, including desmoglein-2 (DSG2), plakoglobin (PG), and desmoplakin (DP)." (PMID 32841221, 2020). "The risk of cardiac disease (ARVC or HCM) for relatives only carrying the DSG2 variant remained unknown." (PMID 30847665, 2019). "This study is the first to evaluate dogs of various breeds and cardiac diseases for the presence of autoantibodies to the desmosomal protein, desmoglein-2." (PMID 36977772, 2023). "This prospective study is the first to evaluate dogs of various breeds and cardiac disease state for anti-desmoglein-2 antibodies." (PMID 36977772, 2023). "A Japanese study on 9 cases of SUDEP performed next-generation sequencing to examine 73 genes related to inherited heart disease: the Authors found KCNE1 as pathogenic variants (together with KCNE1) and also 3 other potentially pathogenic variants (MYH6, DSP, DSG2) according to in silico analysis." (PMID 41062843, 2026). "Mutations in desmosomal genes have been observed in 50% of patients with arrhythmogenic heart disease, and these are represented by mutations in the genes for Plakophilin C (PKP2), Desmoplakin (DSP), Desmocollin-2 (DSC2), Desmoglein-2 (DSG2), and Plakoglobin (JUP)." (PMID 40361967, 2025). "Our results indicate that anti-desmoglein-2 antibodies are present in all dogs, regardless of breed or cardiac disease." (PMID 36977772, 2023).
cardiovascular disease (3 papers, 2022 to 2024). "In addition, it is known that ZDHHC5 is a palmitoyltransferase that modulates the activity of many proteins, some of them known cardiovascular disease-causing genes such as desmosomal cadherin desmoglein-2 (DSG2) and myelin regulatory factor (MYRF)." (PMID 37160609, 2023). "We screened 404 genes related to inherited cardiovascular disease and confirmed that no deleterious mutations were present in other desmosomal genes, including DSC2, DSG2, JUP, and DSP, involved in the etiology of AC." (PMID 35063130, 2022).
digestive system cancer (1 paper, 2022). A primary or metastatic malignant neoplasm involving any part of the digestive system. "The association between DSG2 and clinicopathological features in NSCLC and digestive system cancer." (PMID 35345582, 2022). "In digestive system cancer, DSG2 expression was not statistically correlated with OS (HR = 0.68, 95% CI [0.37–1.24], I2 = 84%, random-effect model)." (PMID 35345582, 2022).
respiratory disease (1 paper, 2023). "Finally, DSG2 has been identified as the primary high-affinity receptor used by a number of adenovirus (Ad) serotypes which cause severe respiratory disease in humans." (PMID 37095599, 2023).
DSG2 also shares sentences with these, for which no sentence is quoted: cardiac arrhythmia (3 papers); hypertrophic cardiomyopathy (3); pemphigus vulgaris (3); adenocarcinoma (2); Alzheimer disease (2); Cardio-cutaneous syndromes (2); Carvajal syndrome (2); dilatation (2); gallbladder carcinoma (2); Left Ventricular Non-Compaction Cardiomyopathy (2); Long QT syndrome (2); meningioma (2); ovarian serous carcinoma (2); ventricular fibrillation (2); ankylosis (1); asthma (1); atrial fibrillation (1); atrial septal defect (1); autosomal dominant inherited disorders (1); bladder urothelial carcinoma (1); brain tumor (1); Brugada syndrome (1); cardiac arrest (1); catecholaminergic polymorphic ventricular tachycardia (1); cervical squamous cell carcinoma (1); chorioamnionitis (1); chronic myeloid leukemia (1); coeliac disease (1); congenital hypothyroidism (1); cutaneous squamous cell carcinoma (1).
A further 43 diseases each share a sentence with DSG2 in 1 paper.